EEF2K (eukaryotic elongation factor 2 kinase)
Diseases named in the same sentence as EEF2K in open-access papers (continued):
Sharing a sentence is not in itself a finding about the gene and the disease.
tumor (continued). "Collectively, these mechanisms account for the cytoprotective role of EEF2K in tumour development." (PMID 35184394, 2022). "In addition, a significant decrease in SPP1 mRNA level was found in EEF2K knockdown tumour xenografts." (PMID 35184394, 2022). "The compound EEF2K is a protein synthesis elongation factor overexpressed in various types of cancer, which plays important roles in activating autophagy, maintaining cellular energy and supporting tumour cell survival under various stressful conditions." (PMID 35408842, 2022). "Several mechanisms have been proposed for the cytoprotective role of EEF2K in tumour development." (PMID 35184394, 2022). "On the other hand, our study uncovers a previous unknown mechanism that the anti-tumor properties of Rhoifolin and Oleuropein may be partially mediated by the inhibition of eEF2K activity." (PMID 35956836, 2022). "The hematoxylin and eosin (H&E) staining of the tumor specimens showed that there were considerably greater amounts of tumor cells in the xenografts from the mice treated with the CEA-specific eEF-2K KO CAR-T cells than in the xenografts from the mice receiving the WT CEA CD8+ CAR-T cells." (PMID 35108044, 2022). "In addition, the tumor-inhibitory effect of WT CEA CD8+ CAR-T cells was significantly weakened when eEF-2K was ablated." (PMID 35108044, 2022). "Moreover, exogenous administration of miRNA-22, loaded in nanoparticles to prevent degradation and improve tumor delivery (termed miRNA-22 nanotherapy), to suppress eEF2K production has shown potential as an investigational therapeutic agent in vivo." (PMID 35294699, 2022). "Furthermore, eEF2K expression is required for drug or signalling responses that suppress tumorigenesis, giving it tumour suppressive activity." (PMID 34895463, 2021). "Several studies have suggested the role of eEF2K in tumour progression and chemoresistance in TNBC." (PMID 34575883, 2021). "Therefore, stimulating eEF2K-eEF2 axis to suppress tumor requires serious assessment, and more in-depth studies are required to comprehensively evaluate its effectiveness from a treatment perspective." (PMID 35127825, 2021). "In addition, eEF2K can also participate in the regulation of the tumor cell cycle, proliferation, autophagy, apoptosis, angiogenesis, invasion, and metastasis, among other processes." (PMID 33673713, 2021). "Inhibition of eEF2K expression can likewise prevent these tumor processes." (PMID 33673713, 2021). "Interestingly, in tumor cells with eEF2K at knocked down levels, compound 1 was still anti-proliferative." (PMID 33673713, 2021). "Some studies have found that eEF2K activators can also have certain anti-tumor effects." (PMID 33673713, 2021). "eEF-2k is a Ca2+/CaM-dependent member of the kinase family function, by phosphorylating/inactivating eEF-2K at threonine 56, leading to reduced peptide chain elongating, then increasing eEF-2K function, promoting tumor cell survival, growth, and metastasis." (PMID 35010954, 2021). "Tumour cells adaptation and survival to the microenvironment was shown to be modulated by eEF2K." (PMID 34575883, 2021). "Conflicting mechanistic data as to whether eEF2K promotes or suppresses tumour growth expand this therapeutic potential further, as the pathway could be susceptible to either activation or suppression." (PMID 32298235, 2020). "Nude mice was utilized to study the correlation of eEF2K and tumor growth in vivo." (PMID 32054489, 2020). "All these pieces of evidence support EEF2K as a tumor-suppressor gene in CRC." (PMID 31266475, 2019). "In general, the downregulation of EEF2K in tumor tissues was significant." (PMID 31266475, 2019). "Cell culture and xenograft experiments using a variety of cancer cell lines, however, point out that eEF2K may exhibit tumor-protective effects by decreasing energy consumption when nutrients are limiting." (PMID 29610153, 2018).
tumor (continued). "In these studies, either suppression of eEF2K activity by its inhibitors, or genetic ablation of eEF2K, effectively slowed down cancer cell migration or invasion and/or significantly prevented tumour growth in xenograft animal models." (PMID 29186827, 2017). "A screen utilising a panel of kinase inhibitors revealed that survival of cells derived from primary tumours from this model growth was impaired by either of two compounds that inhibit eEF2K (TX-1718 and NH125; please refer to comment above about this latter compound)." (PMID 29186827, 2017). "eEF2K is activated and overexpressed in many tumours/cancers." (PMID 29186827, 2017). "One important question these data raise is ‘how does eEF2K affect tumorigenesis and tumour growth’?" (PMID 29186827, 2017). "There are also data indicating that eEF2K promotes tumour growth in vivo." (PMID 29186827, 2017). "Moreover, eEF-2K regulates EMT, through modulation of the TCF8/ZEB1, Snail and claudins, further linking eEF-2K to malignant tumour progression." (PMID 25215932, 2014). "Treatment with both liposomal eEF-2K siRNA#1 and siRNA#2 resulted in significant down-regulation of its expression in the tumors, a decrease in phosphorylated eEF2 and significant inhibition of tumor growth." (PMID 22911754, 2012). "Thus, by facilitating ICL repair, eEF2K may allow tumor cells to tolerate cisplatin treatment at certain doses, which could in the long term lead to the emergence of cisplatin-resistant tumor clones." (PMID 39003251, 2024). "Interestingly, EEF2K plays a paradoxical role in tumour progression." (PMID 35184394, 2022). "It was initially speculated that this cytotoxic activity of 30 is related to its inhibitory effect on PKC, but it was later found that 30 induces tumor cell apoptosis through inhibition of eEF2K by using reverse phase-protein array (RPPA), cell viability (MTS) assay, and eEF2K knockdown technology." (PMID 33673713, 2021). "In addition, our study demonstrated that eEF-2K also facilitates tumor cells growth by promoting a shift from oxidative phosphorylation to glycolysis, and inhibiting eEF-2K can switch off the metabolic process tumor cells rely on and increase the sensitivity of tumor cells to chemotherapy." (PMID 33144562, 2020). "Activation of eEF2K may be important in tissues such as muscle to slow down protein synthesis when tissue is subject to major demands for ATP and increased anaerobic glycolysis leads to acidosis, or in the tumour microenvironment." (PMID 29186827, 2017). "Thus, eEF2K is required for the resistance of tumours to caloric restriction–induced cell death." (PMID 29186827, 2017). "Our findings revealed that eEF2K serves as a significant marker for poor patient survival and is highly upregulated in PDAC cells and promotes tumor growth." (PMID 40624025, 2025). "In vivo, LHA significantly reduced tumor growth and altered tumor histopathology in a PDAC xenograft model, along with downregulated eEF2K and upregulated pyroptosis executors (GSDMD/GSDME)." (PMID 40567376, 2025). "Our study suggests that eEF2K mediates a complex intratumoral communication network between PDAC cells and macrophages, thereby driving tumor growth and progression." (PMID 40624025, 2025). "As a result, our findings reveal a novel regulatory feedback loop involving eEF2K, MCP-1, and Gas6 in PDAC tumors, which promotes the accumulation of M2-TAMs and enhances tumor aggressiveness." (PMID 40624025, 2025).
tumor (continued). "Taken together, we report here that C1, the first molecular glue of eEF2K, possesses strong anti‐cancer activity in vitro, in vivo, and in TNBC organoids, and elicits a synergistic tumor inhibitory effect with PTX." (PMID 38084501, 2024). "We demonstrated that inhibition of eEF2K decreased PD-L1, increased cytotoxic effect of CD8+ T cells in tumor tissues, enhanced the efficacy of PD-1 mAb treatment." (PMID 35347072, 2022). "In this tumor model, we observed that the tumoricidal effect of WT CAR-T cells was substantially stronger than that of eEF-2K KO CAR-T cells." (PMID 35108044, 2022). "To clarify the correlation between 7 PRGs (BTK, CASP5, EEF2K, GZMA, NR1H2, RIPK3, and SDHB) derived from LASSO Cox regression analysis and immune infiltration in COAD, we applied Tumor Immune Estimation Resource (TIMER) database on these genes." (PMID 35912258, 2022). "Therefore, eEF2K is a negative regulator of protein synthesis, and inhibition of eEF2K activity may have therapeutic significance in preventing the survival of tumor cells and recovering protein translation." (PMID 35127825, 2021). "It is noteworthy that, contrary to its tumor-suppressive role in CRC, EEF2K was frequently found to function as an oncogene in other cancer types." (PMID 31266475, 2019). "Strikingly, all three kinases (i.e. PRKAA1, PRKAA2, and EEF2K) regulating cell metabolism were found to contribute to HGG cell viability, providing a novel tumor vulnerability." (PMID 31420543, 2019). "Mounting evidence demonstrates that eEF2K can regulate the expression of various apoptotic proteins including Bcl-XL, XIAP, c-FLIPL, PI3KCI, and p70S6K to impede apoptosis in the tumor." (PMID 30791936, 2019). "Our analysis demonstrated that EEF2K expression was significantly downregulated in CRC in both unpaired and paired comparison between normal and tumor tissues." (PMID 31266475, 2019). "Univariate analysis of our patient cohort indicated that high tumor grade, advanced TNM staging and low EEF2K expression were predictors for shortened overall survival." (PMID 31266475, 2019). "Caloric restriction increased cell death (apoptosis) in tumour xenografts from RasV12-transformed NIH3T3 cells, and eEF2K overexpression protected against this effect." (PMID 29186827, 2017). "In conclusion, our in vitro and in vivo results indicate that miR-603 acts as a tumor suppressor molecule that can attenuate the proliferation and invasion of TNBC by directly targeting eEF2K expression." (PMID 28036267, 2017). "The results of the current study indicate that in vitro and in vivo overexpression of miR-603 recapitulates the effects of eEF2K suppression in TNBC, including inhibition of tumor cell proliferation, migration, invasion and tumor growth." (PMID 28036267, 2017). "Therapeutic targeting of eEF2K triggers apoptosis and suppresses TNBC tumor growth, in addition to and increased doxorubicin and paclitaxel efficacy." (PMID 28036267, 2017). "Its expression results in inhibition of eEF2K by directly targeting the 3-UTR and the inhibition of tumor cell growth, migration and invasion in TNBC." (PMID 28036267, 2017). "Here we provided the first evidence that eEF2K expression is transcriptionally regulated by FOXM1 and that the FOXM1/eEF2K axis promotes cell TNBC proliferation, survival, migration/invasion and contributes to tumor growth and progression." (PMID 26918606, 2016). "To evaluate the therapeutic potential of eEF2K inhibition in PDAC and its role in tumorigenesis, we administered nanoliposomal (NL) particles carrying eEF2K siRNA or control siRNA to athymic nude mice bearing PANC-1 or MiaPaCa-2 tumor xenografts." (PMID 40624025, 2025). "eEF2K and autophagy play key roles in maintaining aggressive tumor behavior and chemoresistance in TNBC, and eEF2K silencing may be a new strategy for the treatment of TNBC." (PMID 39061201, 2024).
tumor (continued). "The premature and dysfunctional state of eEF-2K KO CD8+ T cells, which likely results from the metabolic reprogramming following activation, significantly weakens their cytocidal activity, tumoricidal action, and tumor infiltration ability." (PMID 35108044, 2022). "In our study, we showed that EEF2K functions as a tumour driver independent of its role in protein synthesis or autophagy induction." (PMID 35184394, 2022). "YY1BM, which functions as a tumor suppressor, binds to multifunctional transcription factor YY1 and blocks its interaction to AR, thus decreasing the expression of Eukaryotic Elongation Factor 2 Kinase (eEF2K) and inducing apoptosis in ESCC." (PMID 34983649, 2022). "The NH125 compound is a widely-reported EEF2K inhibitor, which decreases cancer cell viability by increasing EEF2 phosphorylation to reduce mRNA translation into protein, leading to inhibition of tumour growth." (PMID 35408842, 2022). "eEF-2K increases tumor necrosis factor-alpha (TNF-α), promotes TAM survival and function, induces nitric oxide (NO) in activated macrophages, and contributes to aggressive tumor behaviors." (PMID 35010954, 2021). "To determine the role of eEF2K in tumor growth in mice, we subcutaneously injected A549 cells with or without eEF2K depletion in athymic nude mice." (PMID 32054489, 2020). "Immunoblotting analyses of three tissues as random in each group showed that eEF2K depletion increased STAT3 phosphorylation and c-Myc expression in tumor tissues, supporting that eEF2K regulates STAT3 phosphorylation and c-Myc expression and subsequent tumor growth." (PMID 32054489, 2020). "EEF2K expression was not correlated with patients’ age, gender, tumor location, tumor grade, TNM staging or microsatellite instability (MSI) status." (PMID 31266475, 2019). "In vitro kinase-assays revealed a 4-5 times higher eEF2K activity in tumor tissue lysates as compared to non-tumorous liver lysates." (PMID 28060762, 2017). "This study demonstrates for the first time that miR-603 functions as tumor suppressor in TNBC and its expression plays an important role in TNBC cell proliferation, migration/invasion, and tumorigenesis through the regulation of eEF2K." (PMID 28036267, 2017). "An excellent example of translation-related metabolic adaptation is the recent report that eukaryotic elongation factor 2 kinase (eEF2K), which is activated by AMP-kinase (AMPK), confers survival of MB tumor cells under acute nutrient depletion by blocking translation elongation." (PMID 27180681, 2016). "eEF2K promotes tumor growth and progression and more importantly, in vivo inhibition of eEF2K led to significant suppression of tumor growth in multiple PDAC tumor models in mice with no observed toxicity, suggesting that eEF2K is an actionable novel target in PDAC." (PMID 40624025, 2025). "Additionally, having identified a novel eEF2K-Gas6-MCP-1 positive feedback loop that enhances eEF2K activity and promotes tumor growth and poor prognosis, we hypothesize that similar signaling loops may exist in other solid cancers." (PMID 40624025, 2025). "Furthermore, in vivo targeted genetic inhibition of eEF2K suppressed tumor growth in two different PDAC mouse models, reduced tumor-associated macrophages (TAMs), and induced marked apoptosis in tumor tissues without any signs of toxicity." (PMID 40624025, 2025). "Regardless of whether eEF2K is up-regulated or down-regulated in tumor tissues, it is expected to be a biomarker for poor tumor prognosis and a potential molecular target for targeted therapy." (PMID 39592671, 2024). "AMPK or mTOR may phosphorylate eEF2 in the absence of active eEF2K, ensuring that protein synthesis is finely modulated to promote tumor survival under adverse conditions." (PMID 39592671, 2024). "Furthermore, we analyzed and compared the functional profile of the tumor-infiltrating CAR-T cells with or without depletion of eEF-2K." (PMID 35108044, 2022).
tumor (continued). "The results from HPA database showed that the immunohistochemical staining intensity of SDHB, GZMA, BTK, EEF2K, and NR1H2 in glandular cells of normal tissues was stronger than tumor cells, demonstrating that these genes were significantly expressed in normal colon tissues than in tumor tissues." (PMID 35912258, 2022). "Furthermore, the antitumor efficacy and tumor infiltration of the CAR-CD8+ T cells lacking eEF-2K were notably reduced as compared to the control CAR-CD8+ T cells." (PMID 35108044, 2022). "Therefore, although eEF2K does not directly drive tumorigenesis, low eEF2K activity ensures there is no blockade of translation or proliferation in tumour cells." (PMID 34895463, 2021). "We presented an interesting hypothesis whereby eEF-2K and TG2 form a mutual positive regulatory loop in modulation of β1 integrin-dependent signalling to promote the invasive phenotype of PANC-1 and MIAPaCa-2 cells, facilitating the tumour progression in these cells." (PMID 25215932, 2014). "Unlike MAT2A and MAT2B, which are strongly related to HCC, EEF2K is increased in many cancers, including HCC, allowing tumor growth and resisting cell death." (PMID 24098708, 2013). "The tumor suppressor PDCD4, which we have previously shown to up-regulate p27Kip1 expression, was also induced upon eEF-2K down-regulation (data not shown)." (PMID 22911754, 2012). "There was no alteration in the number or cumulative size of tumours in the ageing model at endpoint, again identifying tumour cell proliferation, rather than tumour initiation, as the principal factor regulated by RPL24 and eEF2K." (PMID 34895463, 2021). "Moreover, and most relevant for this review, cells lacking eEF2K show decreased sensitivity to NFR and NFR’s ability to block tumour growth in vivo is markedly reduced when eEF2K is knocked out." (PMID 29186827, 2017).